INS (insulin)
Diseases named in the same sentence as INS in open-access papers (continued):
Sharing a sentence is not in itself a finding about the gene and the disease.
Insulin resistance (continued). "Phenotypic characterisation of cellular expression of SVF-derived pre-adipocytes suggested a heterogeneity in the plasticity of SVF cells between insulin sensitivity and insulin resistance, perhaps accounting for the reduced adipogenic capacity seen in the IR individuals." (PMID 27342408, 2016). "It has been reported that insulin sensitivity can be reduced by stimulating the secretion of free fatty acids, tumor necrosis factor α, and resistin from enlarged adipocytes, and there is a correlation between insulin resistance and the visceral fat load." (PMID 26767080, 2016). "The reduced release of adiponectin by adipocytes, together with a deregulation of insulin intracellular pathway in adipocytes, may contribute in the development of insulin resistance and impairment of glucose metabolism induced by BPA exposure." (PMID 27782064, 2016). "To investigate whether GNMT deficiency contributes to the metabolic phenotype arising from glucose intolerance and insulin resistance, we applied a glucose tolerance test and an insulin tolerance test to a Gnmt−/− mouse model." (PMID 27716281, 2016). "Moreover, MIF is a necessary mediator of TNF-α, which inhibits the insulin signal transduction leading to insulin resistance." (PMID 27298517, 2016). "A plausible hypothesis is that PDI's procoagulant reactions could be increased in insulin resistance and OxS in detriment of decreased insulin activity or even that insulin resistance could be, at least in part, accounted for increased PDI activity." (PMID 28053690, 2016). "Moreover, prebiotics increased the expression of IRβ in CPF1-exposed rats suggesting an enhancement of insulin sensitivity and a decrease of insulin resistance in these animals." (PMID 27760213, 2016). "Reduced sensitivity to the actions of insulin, i.e. insulin resistance, is one mechanism through which CKD may promote CVD." (PMID 27876008, 2016). "The Bangladesh MINIMat and Nepal Janakpur trials measured blood pressure, while the Nepal Sarlahi trial investigated metabolic syndrome (blood pressure, HbA1c, urine microalbumin:creatinine, cholesterol, glucose, insulin, homeostasis model assessment of insulin resistance)." (PMID 27306908, 2016). "Impaired GLUT4 expression, GLUT4 translocation and/or insulin pathway may lead to insulin resistance and hyperglycemia." (PMID 27271603, 2016). "Interestingly, Nlrp3−/− and ASC−/− mice on a HFD for one year had increased insulin levels but were still protected against insulin resistance, displaying β-cell compensatory protective mechanisms at play." (PMID 27128935, 2016). "Type 2 diabetes, is related to either insulin resistance or impaired insulin secretion." (PMID 27058520, 2016). "With advancing age, persistent insulin resistance along with a progressive reduction in circulating insulin levels (due to declining β-cell function), with a concomitant reduction in insulin sensitivity, aggravates glucose disturbances leading to glucose intolerance and DM." (PMID 27872738, 2016). "However, despite the importance of macrophages in obesity-induced insulin resistance, the role of macrophage autophagy in regulating insulin sensitivity is seldom addressed." (PMID 27229537, 2016). "Dietary patterns that induce excessive insulin secretion may contribute to worsening insulin resistance and beta-cell dysfunction." (PMID 27070641, 2016). "This leads to a state of oxidative stress which, in turn, leads to cellular and molecular damage to proteins, lipids and DNA, affecting key insulin signaling molecules and as a result leading to hyperglycemia and hyperinsulinemia, a condition known as insulin resistance." (PMID 26934053, 2016). "In patients with Type 2 diabetes, for a given level of glycaemia, some patients will have marked insulin resistance, with robust but insufficient insulin secretion, while others will have very low insulin secretion but be very, but insufficiently, insulin‐sensitive." (PMID 26802434, 2016).
Insulin resistance (continued). "Furthermore, the PH supplementation also decreased plasma glucose, insulin, glucagon, and homeostasis model assessment of insulin resistance levels." (PMID 26891322, 2016). "Moreover, the HOMA-IR index, a parameter for evaluating the degree of insulin resistance, and quantitative insulin sensitivity check index (QUICKI) were significantly reversed in a dose-dependent manner by the administration of OFS in db/db mice." (PMID 27941667, 2016). "Furthermore, obesity itself has been related to increased endogenous insulin secretion, decreased insulin clearance, and increased insulin resistance." (PMID 26913058, 2016). "Inflammation pathways were coordinately up-regulated with insulin resistance and adipokines, e.g., the chemokine signaling pathway correlated with insulin sensitivity (Matsuda index) (r = −0.807), fs-insulin (r = 0.858), fs-adiponectin (r = −0.598) and leptin (r = 0.428) (p < 0.001 for all)." (PMID 27080554, 2016). "Insulin resistance also induces the expression of key inflammatory cytokine genes such as interleukin 1-beta in macrophages due to the interaction of NF-κB and FoxO1, a key transcription factor mediating insulin action." (PMID 27189661, 2016). "Here, we show that two Wnt proteins, WNT3a and WNT4, are specifically secreted by skeletal muscle and adipose tissue during the development of insulin resistance and play an important role in cross-talk between insulin-resistant tissues and pancreatic beta cells." (PMID 27527335, 2016). "Markers of microbial fermentation of FOPS, including total SCFA, acetate, and cecal weight were negatively correlated with many host metabolic markers, including body weight gain, fasting glucose, fasting insulin, index of insulin resistance, C-peptide, adipose tissue weights, resistin, and leptin." (PMID 26731528, 2016). "Given that glucocorticoids are able to induce insulin resistance, it is plausible that their insulin-desensitising effects may be mediated, at least in part, through increased REDD1." (PMID 27613400, 2016). "Metformin, an insulin-sensitizer, may improve vascular function and several physiologic abnormalities related to insulin resistance with fewer reported side-effects in patients with type 2 DM10." (PMID 27805009, 2016). "Additionally, the ApoE, PTP1B and RBP4 lipometabolic regulators linked with obesity and insulin resistance were upregulated in PLB4 mouse liver, suggesting decreased hepatic insulin sensitivity." (PMID 27138913, 2016). "The aim of the present study was to assess the extent to which elevation of MCP-1 production in muscle and elevated MCP-1 levels in plasma may be able to interfere with insulin signalling in skeletal muscle and promote insulin resistance." (PMID 26661101, 2016). "Maternal obesity, overnutrition(e.g., diets high in fat) and undernutrition (e.g., low protein and/or calorie intake)during gestation and/or lactation result in increased insulin secretion, obesity,insulin-resistance, type 2 diabetes and cardiovascular diseases (24, –26)." (PMID 27828666, 2016). "Although insulin treatment was effective at decreasing insulin resistance in a previous study, it is important to emphasize that the glycemic levels in our study were elevated; therefore a higher dose of insulin could promote a decrease in insulin resistance." (PMID 27579154, 2016). "Estimation of insulin resistance using either levels of insulin, HOMA-IR, glucose, or the ratio of triglycerides and high-density lipoprotein-cholesterol (TG/HDL-C) could potentially improve on cardiovascular risk stratification." (PMID 27275336, 2016). "Taken together, the attenuation of glomerular insulin signaling cascade accompanied with insulin resistance and DM could be related to the emergence and progression of diabetic nephropathy." (PMID 27247938, 2016).
Insulin resistance (continued). "Interestingly, miR-96 was upregulated in the liver of insulin resistant mice injected with resistin, which is considered a potential adipokine responsible for obesity-mediated insulin resistance, T2DM, and inflammation." (PMID 28036389, 2016). "Indeed, elevated circulating insulin concentration and perceived insulin resistance with hypoxic treatment are a finding that has some support." (PMID 27274997, 2016). "Furthermore, the changes in lipid and insulin metabolism seen in preeclampsia suggest a state of increased insulin resistance similar to the metabolic syndrome and persist several years postpartum." (PMID 27558088, 2016). "In line with this hypothesis, insulin-mediated vasodilatation is impaired with insulin resistance and increased BP." (PMID 27973411, 2016). "On the other hand, it would also be of future interest to assess whether DVC GlyT1 inhibition reverses insulin resistance in type 2 diabetic and obese rodents using the hyperinsulinemic–euglycaemic clamp technique to achieve insulin-stimulated conditions." (PMID 27874011, 2016). "Decreased insulin secretory capacity had a stronger effect on 2 h PG elevation in the studies of Japanese, Korean, and Chinese subjects, while insulin resistance had a stronger involvement in 2 h PG elevation in other studies in Caucasian, Pima Indian, American, and Finnish studies." (PMID 26788515, 2016). "Many previous studies have shown that insulin resistance and elevated insulin levels may play an important role in NAFLD." (PMID 26938785, 2016). "However, increased physiological demand for insulin, such as in insulin resistance, can lead to β cell dysfunction and type 2 diabetes." (PMID 27226575, 2016). "Furthermore, a significant decrease in insulin levels was reported, suggesting a reduction in insulin resistance." (PMID 28042834, 2016). "Of note, an impaired brain activity in the slow frequency range with reduced locomotion could be revealed in diet-induced insulin resistant mice, and this went along with brain insulin resistance on the molecular level." (PMID 27589235, 2016). "Expansion of visceral adipose tissue secondary to chronic over-consumption of calories stimulates the recruitment of macrophages, which assume an inflammatory phenotype and produce cytokines that directly interfere with insulin signaling, resulting in insulin resistance." (PMID 27437032, 2016). "If supplied with exogenous netrin-1 to patients could increase insulin sensitivity and improve insulin resistance." (PMID 27255377, 2016). "SR treatment could significantly attenuate hyperlipidemia, which would be corroborated with the reversal of insulin resistance coupled with elevation of insulin secretion." (PMID 27893829, 2016). "Therefore, the alteration of gut microbiota is a contributing factor in the development of insulin resistance, which highlights the potential for improving insulin sensitivity by modulating gut microbiota." (PMID 26999104, 2016). "Increased circulating irisin levels might lower fasting insulin levels (standardized path coefficient = −0.046, p = 0.032), which in turn improves insulin resistance." (PMID 27473122, 2016). "In our model, we observe that about 49% of the population of exposed mice develop symptoms of insulin resistance and metabolic syndrome, with increases in fasting blood glucose, fasting serum insulin, and HOMA-IR index, leading to ectopic accumulation of fat in the viscera." (PMID 26934053, 2016). "At high doses of next-generation BET inhibitors, patients with insulin resistance and Type 2 diabetes might benefit from both increased insulin stores and increased β-cell capacity to oxidize FA, protecting the β-cell from excess nutrient-induced damage." (PMID 27008626, 2016).
Insulin resistance (continued). "Several studies provided strong evidence that chronic HCV infection promotes insulin resistance directly via interference with the intracellular insulin signalling cascade, increase of proinflammatory cytokines or downregulation of the glucose transporter-4 and -2 in skeletal muscle and liver." (PMID 26735686, 2016). "In conclusion, we suggest that decreased Ca2+ levels and increased CaSR expression might be involved in increased insulin secretion to compensate for insulin resistance in aged mice." (PMID 27441644, 2016). "However, sustained hyperinsulinemia or insulin resistance can lead to progressive decline in endothelium-dependent vasodilation, as well as impairment of transcapillary insulin transport to skeletal muscle cells in vivo." (PMID 26770984, 2016). "Data showed that by month 4 of the special diet these animals had already developed at least 3 of the cardinal features of MetS (central obesity, dyslipidemia, and hypertension) and serial evaluation of glucose and insulin levels revealed a progression toward insulin resistance." (PMID 27819007, 2016). "Consequently, the enzyme inhibits inflammation and insulin resistance, as measured by fed and fasting insulin and by HOMA-IR." (PMID 27597806, 2016). "A major challenge in the field of insulin resistance is to monitor this process dynamically in individual cell types of insulin target tissues that are composed of different cell types, such as fat, liver, brain, kidney or pancreatic islets in the living organism." (PMID 26899548, 2016). "Eight horses were defined as insulin resistant (IR) and five horses had normal insulin sensitivity." (PMID 27766986, 2016). "Furthermore, our data are in agreement with those showing that TLR-4 knockout mice are protected against high-fat diet-induced obesity, inflammation, and insulin resistance and exhibited reduced insulin-mediated changes in systemic glucose metabolism." (PMID 27881903, 2016). "The two compounds were also equally effective in normalizing blood glucose and serum insulin levels, as well as in attenuating glucose intolerance and insulin resistance, as measured by the HOMA-IR and insulin sensitivity indices in both mouse genotypes and sexes." (PMID 27900261, 2016). "Impaired insulin signaling in classical insulin target organs (e.g., muscle, adipose tissue, etc.)may lead to metabolic complications, including development of insulin resistance." (PMID 27446805, 2016). "The impairment of PI3K-Akt-mediated insulin signaling induces insulin resistance." (PMID 27187341, 2016). "The formation of insulin resistance is associated with dysbiosis, whereas probiotic or TNF-α antibody can reduce the release of inflammatory cytokines and inhibit SIBO, leading to an improvement in insulin sensitivity." (PMID 26999104, 2016). "1,25(OH)2D may induce insulin secretion and was shown to contribute to a decrease in insulin resistance; therefore, low levels of this vitamin may play a role in the development of GDM." (PMID 27690002, 2016). "Furthermore, we tested their clinical applicability in assessing insulin resistance and dysregulation by analysis of basal blood and blood samples obtained during a dynamic diagnostic stimulation test (OGT) with elevated insulin concentrations." (PMID 27613127, 2016). "Therefore, in this study we aimed to compare CS test results and RNFL and GCIPL thicknesses between patients with insulin resistance and healthy subjects in order to evaluate the structural and functional effects of impaired insulin sensitivity on the retina." (PMID 28050322, 2016). "Interestingly, at old age, male C2αD1268A/WT mice did display glucose intolerance and insulin resistance, greatly contrasting the unaltered insulin signalling observed in insulin-sensitive tissues." (PMID 27138914, 2016).
Insulin resistance (continued). "Our first hypothesis regarding the mechanism by which a bout of physical inactivity rapidly induces muscle insulin resistance is the activation of proinflammatory/stress pathways that restrain insulin signaling and insulin‐stimulated glucose uptake." (PMID 27482072, 2016). "ANGPTL8 level was associated with blood glucose, insulin, and insulin resistance as measured by homeostatic model assessment-insulin resistance (HOMA-IR) in the nondiabetic subjects only." (PMID 27672665, 2016). "Increased insulin resistance as a result of inflammation could affect vasodilation by impairing the vasodilation effect of insulin." (PMID 27846870, 2016). "Insulin resistance was calculated using the quantitative insulin sensitivity check index." (PMID 27296438, 2016). "Due to its key role in insulin sensitivity, this adipokine might be one of other factors involved in the improvement of insulin resistance in the SG." (PMID 27090218, 2016). "Insulin resistance leads to an enhancement of glucose-stimulated insulin secretion (GSIS)." (PMID 27633083, 2016). "Consistently, at skeletal muscle level, FD also attenuated tissue insulin resistance, modulating insulin signalling, restoring protein kinase B (PKB/Akt) phosphorylation and decreased lipid accumulation, increasing ADRP levels, involved in the proper TG storage, and AMPK activation." (PMID 26901315, 2016). "It is hypothesized that this metabolite is part of a compensatory mechanism upregulating pancreatic insulin secretion to maintain glucose homeostasis in early insulin resistance." (PMID 26636104, 2016). "Excess blood glucose level increases the production of free radicals and advanced glycated end-products (AGE) that may inhibit proteins and enzymes involved in the insulin signaling pathways leading to the development of insulin resistance." (PMID 28050570, 2016). "This is in line with a study showing the association of vitamin D deficiency with insulin resistance (higher insulin and HOMA-IR) in Caucasians and East Asians, but not in South Asians." (PMID 26809065, 2016). "Medications such as metformin, TZD, and exogenous insulin could potentially alter the degree of insulin resistance and therefore affect the relevance between betatrophin and insulin resistance." (PMID 26649318, 2016). "Interestingly, recent evidence suggests that although hyperinsulinemia is beneficial to restore euglycemia acutely, the actions of chronically high insulin levels can promote adipose tissue dysfunction and insulin resistance." (PMID 27226575, 2016). "An important implication of hyperinsulinemia that needs to be clearly established is whether neoplastic cells in patients with insulin resistance remain sensitive to insulin’s proliferative actions." (PMID 27437032, 2016). "Adiponectin increases insulin sensitivity, while resistin increases insulin resistance." (PMID 27651836, 2016). "To determine whether STZ/NA-treated mice developed insulin resistance, we next measured serum insulin levels." (PMID 27783671, 2016). "Our result also showed that a cereal fiber supplement decreased the levels of serum insulin, and oat fiber, rich in soluble fiber, may be better for insulin resistance than wheat bran fiber, rich in insoluble fiber." (PMID 27534844, 2016). "Insulin resistance, a defining feature of type 2 diabetes, is a state in which physiological concentrations of insulin produce a less than normal response, thereby impairing the capacity of insulin targets to address the metabolic needs of the body." (PMID 26993044, 2016). "Consumption of PF and PJ ameliorated insulin resistance, suggesting that improved insulin sensitivity might partially explain the anti-obesity effects of the two fruit extracts." (PMID 27058520, 2016). "Type-2 diabetes is characterized by ineffective use of insulin, called insulin resistance." (PMID 26930065, 2016).